SOX2 (SRY-box transcription factor 2)
Diseases named in the same sentence as SOX2 in open-access papers (continued):
Sharing a sentence is not in itself a finding about the gene and the disease.
mesothelioma (4 papers, 2020 to 2024). A usually malignant and aggressive neoplasm of the mesothelium which is often associated with exposure to asbestos. "We designed this study to determine the expression of the most important pluripotency genes and proteins, OCT4, NANOG and SOX2 in human mesothelioma and to investigate its association with the PI3K-AKT-BCL2 pathway." (PMID 32664372, 2020). "Thus, our results indicate that increased activity of PI3K-AKT pathway is likely associated with observed upregulation of NANOG and SOX2 in human mesothelioma." (PMID 32664372, 2020). "Our study demonstrates that NANOG and SOX2 genes and proteins are expressed in human mesothelium and mesothelioma and they may have diagnostic potential." (PMID 32664372, 2020). "In the mouse model of mesothelioma, the H226 cell-derived xenografts, the levels of Sox2 and Oct4 were high in si-NT-treated tumors, but their levels were highly reduced in tumors treated with si-m/hVDAC1-B." (PMID 35883451, 2022). "Immunocytochemical analysis showed that human mesothelioma line exhibited similar pattern of OCT4, NANOG and SOX2 protein expression, and that subcellular localization of NANOG and SOX2 corresponded to human mesothelioma samples." (PMID 32664372, 2020). "The subcellular localization analysis of pluripotency factor protein expression showed that NANOG and SOX2 were expressed in the nucleus and cytosol of human mesothelioma and Mero-14 cells." (PMID 32664372, 2020). "Unlike protein expression, the genes of pluripotency factors, POU5F1, NANOG and SOX2, were less expressed in mesothelioma than in mesothelium." (PMID 32664372, 2020). "This is the first study that extensively tested the expression of OCT4/POU5F1, NANOG and SOX2 genes and proteins in human mesothelium and mesothelioma." (PMID 32664372, 2020). "Comparison of Im index showed a greater expression of NANOG and SOX2 proteins in mesothelioma than in mesothelium, indicting a dedifferentiation of mesothelioma compared to mesothelial cells from which mesothelioma originates." (PMID 32664372, 2020). "Although NANOG and SOX2 genes were downregulated in mesothelioma compared to mesothelium, their proteins were upregulated in the cancer." (PMID 32664372, 2020). "Similar to their proteins, NANOG and SOX2 genes were expressed in both mesothelium and mesothelioma." (PMID 32664372, 2020). "Since protein expression is directly related to cellular phenotype and therefore more relevant than gene expression, our results indicate that mesothelioma has upregulated NANOG and SOX2 pluripotency factors compared to mesothelium, its tissue of origin, indicating dedifferentiation of mesothelioma." (PMID 32664372, 2020). "Others have shown that H2O2 can upregulate POU5F1, NANOG and SOX2 in mesothelioma line." (PMID 32664372, 2020). "This suggests that NANOG and SOX2 are expressed almost in all cell subpopulations of mesothelioma." (PMID 32664372, 2020). "Compared to normal mesothelium, mesothelioma exhibited higher expression of NANOG and SOX2 proteins and lower expression of POU5F1, NANOG and SOX2 genes." (PMID 32664372, 2020). "Human mesothelium and mesothelioma expressed SOX2, NANOG, PI3K and AKT genes and proteins and POU5F1 gene, whereby NANOG, SOX2 and phosphorylated (activated) AKT were upregulated in mesothelioma." (PMID 32664372, 2020). "Mesothelioma cell line recapitulated the expression pattern of OCT4, NANOG and SOX2 proteins in human mesothelioma." (PMID 32664372, 2020). "In conclusion, human mesothelioma displays enhanced expression of NANOG, SOX2 and phosphorylated AKT proteins, while elevated NANOG expression correlates with poor differentiation of human mesothelioma." (PMID 32664372, 2020). "We demonstrated that human mesothelium and mesothelioma express NANOG and SOX2 proteins and POU5F1, NANOG and SOX2 genes." (PMID 32664372, 2020).
mesothelioma (continued). "Samples of human normal mesothelium and mesothelioma were analyzed pathohistologically and immunohistochemically to determine the expression of the pluripotency factors, OCT4, NANOG and SOX2." (PMID 32664372, 2020). "The mesothelioma samples used for testing OCT4, NANOG and SOX2 expression were also used for investigating the expression of phosphorylated (activated) PI3K (Tyr607; p-PI3K), phosphorylated/activated AKT (Ser473; p-AKT) and BCL2." (PMID 32664372, 2020). "We tested the expression of OCT4/POU5F1, NANOG, SOX2, PI3K-AKT pathway and BCL2 genes and proteins in 65 samples of human mesothelioma and 19 samples of normal mesothelium." (PMID 32664372, 2020). "We showed for the first time in human mesothelioma that PI3K and AKT genes were in positive correlation with the expression of POU5F1, NANOG and SOX2, suggesting positive regulation at the level of gene expression." (PMID 32664372, 2020). "Conversely, it has been also shown that POU5F1, NANOG and SOX2 are not expressed in mesothelioma cell lines." (PMID 32664372, 2020). "In mesothelium and mesothelioma, OCT4 protein was not expressed, but NANOG and SOX2 proteins were expressed in portion of cells." (PMID 32664372, 2020). "Since we showed that wortmannin did not significantly affect the expression of NANOG or SOX2, this suggest that PI3K/AKT pathway does not regulate pluripotency genes in mesothelioma and that pluripotency factors act upstream of it." (PMID 32664372, 2020). "Moreover, by utilizing advantages of immunocytochemical approach, we demonstrated that SOX2 and especially NANOG are expressed in majority of Mero-14 and mesothelioma cells, not just these putative cancer stem cells." (PMID 32664372, 2020).
metastasis (4 papers, 2014 to 2022). The spread or migration of cancer cells from one part of the body (where they first appeared) to another. "For OSCC, Sox2 expression is a controversial marker considering that some studies have reported Sox2 to be linked to lymph node metastasis and poor survival, while others have found increased Sox2 expression to improve prognosis." (PMID 35296132, 2022). "For this, 13 patients with archival tissue from both a primary colorectal adenocarcinoma and distant liver metastasis were included in the study and nuclear SOX2 expression was evaluated in epithelial cells." (PMID 25010701, 2014). "Moreover, we have validated some previously reported overexpressed genes such as TGFB1, IBSP, MMP9, or ITGB3 in bone metastasis; CRYAB, NRCAM, and SOX2 in brain metastasis; VEGF and IL6 in lung metastasis; and CYP4F3 in liver metastasis." (PMID 34051058, 2022).
multiple sclerosis (4 papers, 2015 to 2024). A progressive autoimmune disorder affecting the central nervous system resulting in demyelination. "SOX2 is also expressed in Schwann cells and impairs Schwann cell remyelination and functional recovery after nerve injury, as in multiple sclerosis." (PMID 35420440, 2022).
odontogenic cyst (4 papers, 2021 to 2025). A cyst in the jaw that arises from tissues of tooth development. "In conclusion, we report in the present study the differential SOX2 with limited OCT4 expression in odontogenic cysts and tumors." (PMID 34261507, 2021). "This study aimed to assess the prognostic role of SOX2 as a tumor stem cell marker in odontogenic cysts and tumors; it is one of the primary studies which correlate SOX2 immunohistochemical staining scores to different clinical and radiological findings in these common pathologies." (PMID 41176605, 2025). "SOX2 is differentially expressed in odontogenic cysts and tumors." (PMID 34261507, 2021). "Available data in literature suggest that SOX2 is expressed differently in odontogenic cysts and tumors which may reflect their different histogenesis, however, few research correlate SOX2 expression to clinical and radiological findings in benign odontogenic cysts and tumors." (PMID 41176605, 2025). "The objective of this study was to comparatively analyze the expression and significance of SOX2 and OCT4 in various types of odontogenic cysts and tumors." (PMID 34261507, 2021). "In this study, we report the expression of SOX2 and OCT4 in different types of odontogenic cysts and tumors." (PMID 34261507, 2021). "Various stemness markers (SOX2, OCT4, and NANOG) have been studied in odontogenic cysts and tumors." (PMID 38895097, 2022). "Therefore, the objective of this study was to comparatively analyze the pattern of SOX2 and OCT4 expression in various types of odontogenic cysts (DC, OKC, COC) and tumors (AM, AOT, AF)." (PMID 34261507, 2021). "Similarly, botryoid odontogenic cysts and glandular odontogenic cysts did not express SOX2." (PMID 37761874, 2023). "Calcifying odontogenic cysts were positive for CD44, but negative in all or most cases for OCT4 and SOX2, respectively." (PMID 37761874, 2023).
prostate adenocarcinoma (4 papers, 2021 to 2025). "Gene-engineered mouse models further confirm that Sox2 is essential for neuroendocrine differentiation in phosphatase and tensin homolog (Pten)-deficient prostate adenocarcinomas induced by treatment." (PMID 40821114, 2025). "Further studies have shown that in primary prostate adenocarcinoma specimens, SOX2 is typically expressed negatively." (PMID 40821114, 2025). "Sox2 is necessary for androgen ablation-induced NE differentiation of Pten null prostate adenocarcinoma as genetic ablation of Sox2 suppressed NE differentiation." (PMID 39363904, 2024). "SOX2 can repress typical prostate adenocarcinoma genes due to its activation of lysine-specific demethylase 1 (LSD1) that causes the marked global hypomethylation of histone H3." (PMID 39682746, 2024). "NEPC can arise from neuroendocrine transdifferentiation of prostate adenocarcinoma and is orchestrated by global epigenetic modifications mediated by SOX2 and EZH227,34." (PMID 34172788, 2021).
retinal degeneration (4 papers, 2008 to 2025). Degeneration of the retina. "The approach identified genes that cause retinal degeneration (CNGB1, SEMA4A, RRG4) or developmental changes (SOX2) when mutated." (PMID 18334927, 2008). "In mice, Sox2-deficient Müller glia re-enter the cell cycle but do not differentiate into other retinal cell types, eventually leading to retinal degeneration." (PMID 41159420, 2024). "In the retina, SRY-box transcription factor 2 (SOX2) maintains Müller glia in a quiescent progenitor state, and its ablation results in morphological disruption and retinal degeneration." (PMID 41562054, 2025). "In this study, we found that at the early stages of retinal degeneration, Müller cells expressed the proliferative marker BrdU, stem/progenitor markers PAX6 and SOX2." (PMID 27384999, 2016).
tongue cancer (4 papers, 2016 to 2021). A malignant neoplasm affecting the tongue. "Further studies will better the understanding about the mechanisms in MTA3-regulated SOX2 expression in tongue cancer." (PMID 31552166, 2019). "Similarly, another study in tongue carcinoma demonstrated that SOX2 is a key regulator of the cancer epithelial cell plasticity." (PMID 32848819, 2020). "Here, we examined whether introduction of defined reprogramming factors (Oct4, shp53, Sox2, Klf4, l-Myc and Lin28) into HSC2 tongue cancer cells could transform the HSC2 into HSC2 with CSCs properties." (PMID 27464948, 2016). "In this study, we demonstrated that the introduction of defined reprogramming factors (Oct4, shp53, Sox2, Klf4, l-Myc and Lin28) could generate cells with CSC-like properties from a tongue cancer cell line, HSC2." (PMID 27464948, 2016).
urothelial carcinoma (4 papers, 2015 to 2025). A malignant neoplasm derived from the transitional epithelium of the urinary tract (urinary bladder, ureter, urethra, or renal pelvis). "Among 3D organoid, 2.5D early passage organoid, 2.5D late passage organoid, and urothelial carcinoma cell line, mRNA expression level of SOX2 was the highest in 3D organoid." (PMID 32523078, 2020). "Nevertheless, there is no data showing the expression of CD44 or SOX2 mediates the tumor progression in dog urothelial carcinoma." (PMID 32523078, 2020).
adenomyosis (3 papers, 2015 to 2024). The growth of endometrial tissue inside the muscular wall of the uterine corpus. "Whereas, mRNA expression of NANOG, OCT4 and SOX2 in cultured uterine myometrial cells isolated from cows with adenomyosis was increased compared to those isolated from normal uteri (P < 0.05)." (PMID 26416515, 2015). "Protein expression of NANOG and SOX2 was significantly decreased in stromal cells isolated from uteri with adenomyosis compared to those obtained from normal uteri (P < 0.05)." (PMID 26416515, 2015). "However, in stromal cells protein expression of NANOG and SOX2 was significantly decreased in the case of adenomyosis." (PMID 26416515, 2015).
aneurysm (3 papers, 2015 to 2024). Bulging or ballooning in an area of an artery secondary to arterial wall weakening. "In addition, cerebral samples from SAH patients with aneurysm demonstrated the existence of many NSC markers, such as Nestin, vimentin, SOX-2, Musashi-1, and Musashi-2, which possibly contribute to the neural regeneration and functional recovery after aneurysm rupture." (PMID 28133486, 2017).
Azoospermia (3 papers, 2018 to 2023). Absence of any measurable level of sperm,whereby spermatozoa cannot be observed even after centrifugation of the semen pellet. "The results showed that the isolated PGCs expressed cDAZL (chicken azoospermia-like deletion), Nanog, cPou5fl, and Sox-2." (PMID 38136842, 2023).
bladder (3 papers, 2019 to 2023). "Immunohistochemical staining for RAGE and SOX2 antibodies was applied on 87 prostatic biopsies [16 of prostatitis, 20 of benign prostatic hyperplasia (BPH) and 51 of PCa]." (PMID 30806068, 2019). "Moreover, 5637 cell-derived tumorspheres were enriched in active β-catenin and the CSC markers ALDH1A1, Sox-2 and Oct-4, demonstrating that paclitaxel resistance promotes the proliferation of bladder tumorspheres through Wnt/β-catenin pathway." (PMID 35008872, 2021). "Even though there was a minor increment in SOX2 expression in our IL-6-induced prostate tumorspheres, it was not significant." (PMID 37987305, 2023). "Expression of RAGE and SOX2 (percentage of positive cells) was significantly higher in PCa lesions compared with prostatitis (p<0.01) and BPH (p<0.0001) and was also significantly higher in prostatitis compared with BPH lesions (p<0.01)." (PMID 30806068, 2019).
cardiomyopathy (3 papers, 2017 to 2022). A disease of the heart muscle or myocardium proper. "However, Yoshioka and Dowdy also successfully generated iPSCs from adult human fibroblasts of 54- to 77-year-old healthy donors and from a 24-year-old cardiomyopathy patient using srRNA encoding the reprogramming factors Oct4, Sox2, Klf4, Glis1, and cMyc." (PMID 31320906, 2019). "We found that a single transfection of a five factor (5F) srRNA, containing OCT4, KLF4, SOX2, GLIS1 and c-MYC, robustly generated iPSCs from adult human fibroblasts aged 54 to 77 and from a 24 year old cardiomyopathy patient donor." (PMID 28750082, 2017). "We found that five factor srRNA (5F-srRNA), including OCT4, KLF4, SOX2, GLIS1 and c-MYC (OKSi-GM), significantly increased iPSC generation in six different adult human fibroblasts, including old adult fibroblasts and a cardiomyopathy patient donor." (PMID 28750082, 2017).
Cerebral ischemia (3 papers, 2008 to 2022). Restriction of arterial blood supply to the brain associated with insufficient oxygenation to support the metabolic requirements of the tissue. "There were 198 TFs identified after 6 h MCAO operation, and six TFs (Sox2, Smad3, FoxO1, Creb1, Egr,1 and Smad4) were considered as critical TFs in response to cerebral ischemia." (PMID 33414894, 2020).
cervical intraepithelial neoplasia (3 papers, 2015 to 2025). "The aim of the present study was to assess a diagnostic potential of stem cell markers NANOG and SOX2 for classifying cervical squamous intraepithelial lesions (SILs)/cervical intraepithelial neoplasia (CIN)." (PMID 40272007, 2025).
chondrosarcoma (3 papers, 2020 to 2022). A malignant cartilaginous matrix-producing mesenchymal neoplasm arising from the bone and soft tissue. "The effect of miR-34 and miR-142–3 p in radioresistance in chondrosarcoma and ATRT have been identified by regulating the transcription factors FOXO3 and SOX2, respectively." (PMID 36326232, 2022).
COVID-19 (3 papers, 2024 to 2025). A disease caused by infection with severe acute respiratory syndrome coronavirus 2. "In human IPF and COVID-19 damaged lungs, loss of SOX2 correlates with the appearance of aberrant KRT5−/KRT17+ epithelial cells." (PMID 38182591, 2024). "SOX2-deficient dysplastic epithelial cells are also observed in COVID-19 damaged lungs." (PMID 38182591, 2024). "These KRT5−/KRT17+ cells from COVID-19 patients were found to express SOX2 at a lower level than other cell types." (PMID 38182591, 2024).
deafness (3 papers, 2014 to 2020). An inherited or acquired condition characterized by the complete loss of the ability to hear from one or both ears. "Open chromatin regions detected in Sox2-EGFP+ cells map to over 48,000 orthologous regions in the human genome that include regions in genes linked to deafness." (PMID 31227770, 2019).
developmental delay (3 papers, 2017 to 2024). "Moreover, other risk genes for developmental delay, such as BRD3, KBTBD7, and GATA3, also peaked during this stage, whereas SOX2 displayed high expression in a later lineage." (PMID 39363111, 2024).
epilepsy (3 papers, 2017 to 2022). A brain disorder characterized by episodes of abnormally increased neuronal discharge resulting in transient episodes of sensory or motor neurological dysfunction, or psychic dysfunction. "The SOX2-bound genes that are associated with glutamate import and epilepsy were identified as Kcnj10 (Kir4.1), Slc1a2 (GLT-1), and Slc1a3 (GLAST)." (PMID 36543123, 2022).
gastritis (3 papers, 2018 to 2021). Inflammation of the stomach. "NOX1/ROS signaling is suggested to promote proliferation of sex determining region Y (SRY)-box 2 (SOX2)-positive gastric stem cells, which leads to gastritis-associated metaplastic hyperplasia." (PMID 34440074, 2021). "We found that SOX2-expressing cells were increased significantly by NOX1/ROS pathway activation in gastritis-associated hyperplastic mucosa." (PMID 30700829, 2019). "Furthermore, disruption of Noxo1 in K19-C2mE mice significantly suppressed gastritis-associated metaplastic hyperplasia, a potent preneoplastic lesion, which was associated with decreased number of SOX2-positive cells." (PMID 30700829, 2019). "We also detected a significant increase in the Sox2 mRNA level in K19-C2mE gastritis tissues in comparison to the wild-type normal stomach level." (PMID 30700829, 2019). "Moreover, the number of SOX2-expressing cells increased and clustered in the gland neck of hyperplasic lesions of K19-C2mE mouse gastritis, where Ki67-positive cells were localized." (PMID 30700829, 2019). "Notably, among significantly activated pathways in K19-C2mE mouse gastritis compared with normal stomach, the SOX2 pathway was downregulated in apocynin-treated MKN45 cells, indicating that SOX2 is a possible target of NOX1/ROS pathway in gastritis tissues." (PMID 30700829, 2019).
glaucoma (3 papers, 2021 to 2025). Increased pressure in the eyeball due to obstruction of the outflow of aqueous humor. "Finally, SOX2, which has a higher median in the cataract group than the glaucoma group, was excluded." (PMID 40149693, 2025). "The use of the Oct4 (also known as Pou5f1), Sox2 and Klf4 genes (OSK) to reverse DNA methylation during glaucoma and restore vision strongly suggest that PRC2 may be involved in glaucoma as well." (PMID 34502238, 2021).